RN7SL573P (RNA, 7SL, cytoplasmic 573, pseudogene)
Gene: Miscellaneous RNA gene on chromosome 17 (75,041,740 to 75,042,015, forward strand). Ensembl gene ENSG00000239607.
Homologues: Orthologues: chimpanzee Metazoa_SRP (87% identical). Paralogues in human: RN7SL2 (80% identical), RN7SL1 (79% identical), RN7SL3 (79% identical), RN7SL408P (76% identical), RN7SL118P (75% identical), RN7SL481P (75% identical), RN7SL4P (75% identical), RN7SL5P (75% identical), RN7SL296P (74% identical), RN7SL45P (74% identical), RN7SL480P (74% identical), RN7SL7P (74% identical), and 705 more.